WASL (WASP like actin nucleation promoting factor)
Diseases named in the same sentence as WASL in open-access papers (continued):
Sharing a sentence is not in itself a finding about the gene and the disease.
cancer (45 papers, 2009 to 2025). A tumor composed of atypical neoplastic, often pleomorphic cells that invade other tissues. "In general, the N-WASP encoding WASL gene is only rarely altered in cancer, amplifications are more frequent than deletions, and truncations are the minority of the observed mutations, indicating a more oncogenic profile of WASL gene alterations in cancer." (PMID 31608298, 2019). "Collectively, this study establishes FBXW2 as a critical tumor suppressor in GC, operating through ubiquitin-mediated degradation of WASL to inhibit cancer progression." (PMID 40721413, 2025). "The reverse expression of WASL in these two tumor cell lines implies a complicated function of WASL in different cancer types." (PMID 28640862, 2017). "On the other hand more research would be necessary to investigate the CD2AP and WASL co-regulated molecular events during cancer pathogenesis, which might be controlled by Tks4." (PMID 39234565, 2024). "WASL is directly involved in the dynamic regulation of actin filamentous branching in the cytoskeleton, closely related to the negative regulation of lymphocyte migration, and involved in the development and progression of a variety of cancers." (PMID 37980468, 2023). "Very few alterations are reported for N-WASP (WASL) in cancers." (PMID 34196668, 2021). "As indicated by our results, the mRNA expression levels of SRC, CDC42, WASL, and RHO were all changed during cancer cell migration." (PMID 28640862, 2017). "Of these exclusively expressed proteins, only 2 (WASL and LRP5) are involved in metastatic processes and none were reported to be involved in specific tissue-targeted cell homing or organotropic cancer metastasis." (PMID 40410902, 2025).
tumor (39 papers, 2010 to 2025). "Thus, this also suggests a potential association with tumor progression for WASL." (PMID 37623256, 2023). "We conducted a comprehensive bioinformatic analysis to investigate the mRNA and protein expression levels of Tks4 and its associated partner molecules (CD2AP, GRB2, WASL, SRC, CTTN, and CAPZA1) across different tumor types." (PMID 39234565, 2024). "KU treatment downregulated the epithelial-mesenchymal markers Twist, Snail, and Slug and the metastasis-related genes CAPN1, CDC42, CFL1, IGF1, WASF1, and WASL in cells and tumor tissues." (PMID 30390003, 2018). "To determine whether WASL was required for FBXW2-mediated tumor-suppressing effects, we synthesized WASL-overexpressing plasmid to upregulation WASL expression." (PMID 40721413, 2025). "In summary, this study identifies FBXW2 as an essential regulator of malignant GC by suppressing tumor stemness, tumorigenesis and metastasis, which may be at least partially attributed to its targeting of WASL." (PMID 40721413, 2025). "Whether WASL-mediated tumor cell motility and metastatic dissemination affect the progression of GC is unknown." (PMID 40721413, 2025). "Indeed, protrusions essential for in vivo migration and invasion of tumor cells are formed dependent on WASL." (PMID 26657485, 2015). "WASL interacts with components of cellular cytoskeletal network, such as the actin-related protein 2/3 complex, to induce cytoskeletal filament assembly, consequently facilitating invasive behavior of tumor cells and membrane protrusion formation with matrix-degrading activity." (PMID 40721413, 2025). "However, the role of N-WASP (gene name: WASL) in intestinal carcinogenesis remains controversial, with evidence suggesting it may function as a tumor suppressor in early tumorigenesis but exert a pro-invasive role in later metastatic phases." (PMID 39234565, 2024). "Differences in tumor type may contribute to differences in WASL gene function." (PMID 37980468, 2023). "We found that the sensitivity of the WASL, GRB2, SRC, and Tks4 gene expression set was high for both tumor types (0.96 and 0.99), but the specificity values were low." (PMID 39234565, 2024). "Consistently, the confusion matrix statistics showed that the normal and tumor samples can be reliably separated using gene expression data for CD2AP, GRB2, WASL, SRC, CTTN, CAPZA1, and Tks4 with 97% sensitivity and 80% specificity." (PMID 39234565, 2024). "In the case of the TCGA COAD dataset, the combined ROC curve of WASL, GRB2, SRC, and Tks4 gene expression yielded the same high accuracy as before (AUC value = 0.98), indicating that the separation of normal and tumor samples is achievable based on the reduced gene set’s expression data." (PMID 39234565, 2024).
infection (34 papers, 2007 to 2025). The state of being infected such as from the introduction of a foreign agent such as serum, vaccine, antigenic substance or organism. "In a single step growth analysis, WASL KO cells showed 62% reduction in EMCV-infected cells as compared to control cells (p<0.0001), while in a multi-step growth curve, WASL KO cells yielded 248-fold reduced virus titers at 24 hr post infection (p<0.01)." (PMID 31769754, 2019). "Interestingly, transduction of the N-terminal WH1 domain truncated mutant increased EMCV infection by 3-fold compared to wild type WASL transduction." (PMID 31769754, 2019). "In response to infection, cells activate Cdc42, which recruits p120 catenin (p120ctn; also known as δ-catenin 1 or CTNND1), potentially via their shared interactor N-WASP (also known as WASL)." (PMID 38465512, 2024). "After screening a panel of mammalian viruses, we found that multiple picornaviruses, including EMCV, CVB3, enterovirus D68, and poliovirus, rely on TNK2, WASL, and NCK1 for infection in different cell lines." (PMID 31769754, 2019). "Our data represent the first demonstration that WASL and NCK1 are important for infection by picornaviruses such as EMCV, CVB3, enterovirus D68, and poliovirus." (PMID 31769754, 2019). "Here we demonstrate roles for three human genes, TNK2, WASL, and NCK1, in infection by multiple picornaviruses." (PMID 31769754, 2019). "To examine whether EMCV infection recruits WASL as observed for poxvirus, we expressed N-terminal GFP tagged WASL in WASL KO cells." (PMID 31769754, 2019). "The Dextran macropinocytosis defect in the WASL KO appears to be unrelated to EMCV infection though since no reduction in either binding or internalization of EMCV was observed." (PMID 31769754, 2019). "In the absence of either TNK2 or WASL, EMCV particles continued to accumulate in early endosomes at 30 min post infection in contrast to control cells, demonstrating a role for both genes in endosomal trafficking." (PMID 31769754, 2019).
WASL also shares sentences with these, for which no sentence is quoted: colorectal cancer (10 papers); adenocarcinoma (4); clear cell renal cell carcinoma (4); gastric cancer (4); pancreatic cancer (4); esophageal squamous cell carcinoma (3); hepatocellular carcinoma (3); pancreatic ductal adenocarcinoma (3); skin cancer (3); squamous cell carcinoma (3); atopic dermatitis (2); Autoimmunity (2); centronuclear myopathy (2); pancreatic adenocarcinoma (2); psoriasis (2); adenoma (1); alopecia (1); Alzheimer disease (1); amyotrophic lateral sclerosis (1); autism spectrum disorder (1); autoimmune disease (1); cerebral infarction (1); chlamydia infection (1); chlamydial infection (1); colon adenocarcinoma (1); colon polyps (1); colorectal adenoma (1); endometrial cancer (1); epilepsy (1); fibrosis (1).
A further 40 diseases each share a sentence with WASL in 1 paper.